BUB1B (BUB1 mitotic checkpoint serine/threonine kinase B)
Description:
Component of the mitotic checkpoint complex (MCC), which inhibits APC/C and delays chromosome segregation until all chromosomes are properly attached to the mitotic spindle. The MCC, which consists of CDC20, MAD2L1/MAD2, BUB1B/BUBR1 and BUB3, is a key player of the spindle assembly checkpoint. The MCC-bound APC/C complex is inactive and this delays the metaphase/anaphase transition. When the spindle assembly checkpoint is silenced, the MCC-APC/C complex recruits the E2 enzyme UBCH10 and triggers the auto-ubiquitination of CDC20 in the MCC, thereby reactivating APC/C for transition into anaphase. MCC also monitors kinetochore activities that depend on the kinetochore motor CENPE. Required for kinetochore localization of CENPE. Negatively regulates PLK1 activity in interphase cells and suppresses centrosome amplification. May play a role for tumor suppression (By similarity).
Synonyms: hBUBR1; BUBR1; MAD3L; SSK1; Bub1A; BUB1beta; MVA1
Tractability: Small molecule: a high-quality ligand is known; it belongs to a druggable protein family. PROTAC: it is named in the literature on targeted protein degradation; UniProt records ubiquitination sites on it; ubiquitination databases record sites on it.
Target class: Enzyme; Transferase
Gene: Protein-coding gene on chromosome 15 (40,161,023 to 40,221,136, forward strand). Ensembl gene ENSG00000156970.
Subcellular location: Cytoplasm; Nucleus; Chromosome, centromere, kinetochore; Cytoplasm, cytoskeleton, microtubule organizing center, centrosome
Subcellular location (Human Protein Atlas): Cytosol; Basal body
Pathways (Reactome):
Cell Cycle: APC-Cdc20 mediated degradation of Nek2A; APC/C:Cdc20 mediated degradation of mitotic proteins; Amplification of signal from unattached kinetochores via a MAD2 inhibitory signal; Cdc20:Phospho-APC/C mediated degradation of Cyclin A; EML4 and NUDC in mitotic spindle formation; Inactivation of APC/C via direct inhibition of the APC/C complex; Mitotic Prometaphase; Resolution of Sister Chromatid Cohesion; Separation of Sister Chromatids
Signal Transduction: RHO GTPases Activate Formins
Gene Ontology:
Molecular function: protein binding; protein kinase activity; protein serine/threonine kinase activity; protein serine kinase activity
Biological process: mitotic spindle assembly checkpoint signaling; meiotic sister chromatid cohesion, centromeric; regulation of sister chromatid segregation
Cellular component: cytoplasm; cytosol; kinetochore; mitotic checkpoint complex; outer kinetochore; perinuclear region of cytoplasm; spindle; anaphase-promoting complex; nucleus; centrosome
Genetic constraint (gnomAD): Loss-of-function variants: 81 observed, 137.83 expected, observed/expected ratio (o/e) 0.59, 90% interval 0.49 to 0.71. The upper end of that interval is the gene's LOEUF score, 0.71, which puts it in group 2 of 6, group 1 being the genes least tolerant of losing a copy. Missense variants: 1,120 observed, 1,295.5 expected, observed/expected ratio (o/e) 0.86, 90% interval 0.82 to 0.91. Synonymous variants: 420 observed, 442.69 expected, observed/expected ratio (o/e) 0.95, 90% interval 0.88 to 1.03.
Gene-disease validity (ClinGen):
ClinGen rates the evidence that BUB1B causes each of these diseases.
mosaic variegated aneuploidy syndrome 1 (autosomal recessive): Definitive. Any mosaic variegated aneuploidy syndrome in which the cause of the disease is a mutation in the BUB1B gene.
Cancer hallmarks: invasion and metastasis (promotes); genome instability and mutations (suppresses); proliferative signalling (promotes); escaping programmed cell death (promotes)
Homologues: Orthologues: chimpanzee BUB1B (97% identical), macaque BUB1B (95% identical), dog BUB1B (88% identical), pig BUB1B (88% identical), rabbit BUB1B (87% identical), guinea pig BUB1B (81% identical), rat Bub1b (77% identical), mouse Bub1b (75% identical), tropical clawed frog bub1b (45% identical), Drosophila melanogaster BubR1 (24% identical), Drosophila melanogaster Bub1 (20% identical), zebrafish bub1bb (17% identical), and 3 more. Paralogues in human: BUB1 (21% identical).
Diseases named in the same sentence as BUB1B in open-access papers:
BUB1B is named in the same sentence as 180 diseases in open-access papers, as found by Europe PMC text mining. Sharing a sentence is not in itself a finding about the gene and the disease. The quoted sentences say what the papers report.
breast cancer (49 papers, 2006 to 2025). A primary or metastatic malignant neoplasm involving the breast. "Previous work revealed that, high expression of BUB1B is also associated with many other cancers like breast cancer, gastric adenocarcinoma and hepatocellular carcinoma." (PMID 40653567, 2025). "A recent study also correlated the mutation of the BUB1B gene with the onset of pediatric neuroblastoma, bladder cancer, breast cancer, and endometrial carcinoma." (PMID 38664248, 2024). "The BUB1B gene also caused a decrease in the survival probability of the patients suffering from breast cancer and resulting in metastasis in another study." (PMID 36980449, 2023). "A large number of reports have indicated that overexpression of BUB1B is associated with the progression and prognostic of ovarian cancer, hepatocellular carcinoma, prostate cancer, breast cancer and other cancers." (PMID 36577966, 2022). "Studies have found that BUB1B is overexpressed in kidney cancer and breast cancer, its mutation and overexpression are strongly associated with Chromosomal instability." (PMID 35037540, 2022). "Several mutations of BUB1B were associated with cancers such as M40T in colorectal cancer and Q363R in breast cancer." (PMID 35517426, 2022). "MAD2L1 has been documented to be associated with female breast cancer, where it is usually deleted or amplified simultaneously with BUB1B." (PMID 35132379, 2022). "Abnormal expression of BUB1B has turned out to be associated with the development of lung adenocarcinoma, breast cancer, colorectal cancer and prostate cancer." (PMID 31888692, 2019). "Recently, a strong association has been found between BUB1B and other mitotic checkpoint genes and breast cancer risk." (PMID 21785684, 2011). "In addition, the over-expressed BUB1B found in prostate cancer, lung cancer, and breast cancer was associated with the proliferation and metastasis of cancer cells." (PMID 36577966, 2022). "According to the current analysis, we predicted that BUB1B might also be associated with breast cancer, but experimental data were needed to confirm this specific connection." (PMID 33083112, 2020). "In addition, BUB1B is preferentially expressed in high-grade breast cancer, and its expression level exhibits significant associations with long-term survival." (PMID 31285741, 2019). "A variant in BUB1B (p.L373X) occurred in an individual with CM, breast cancer and mesothelioma." (PMID 29641532, 2018). "The aberrant expression of AURKA, BUB1B, CCNA2, CCNB2, and PBK resulted in a poorer survival rate of breast cancer patients in the high-risk group having a survival rate of less than 2 years." (PMID 36980449, 2023). "In this study, we identified 283 overlapping DEGs (105 up- and 178 down-regulated) and six hub genes (RRM2, CDC20, CCNB2, BUB1B, CDK1, CCNA2) associated with breast cancer tumorigenesis and progression based on multiple datasets." (PMID 33083112, 2020). "Overall, we identified five genes (TPX2, KIF2C, CDCA8, BUB1B, and CCNA2) associated with distant metastasis, indicating these genes as potential biomarkers for assessing the risk of breast cancer recurrence and distant metastasis." (PMID 31285741, 2019). "According to the PPI networks, five hub genes (TPX2, KIF2C, CDCA8, BUB1B, and CCNA2) were identified as key genes associated with breast cancer progression." (PMID 31285741, 2019). "Five hub genes, including TPX2, KIF2C, CDCA8, BUB1B, and CCNA2, were validated to be notably associated with the shorter DMFS of breast cancer in the patient cohort based on KM Plotter." (PMID 31285741, 2019). "BUB1B is overexpressed in breast cancer, and the level of BUB1B mRNA is significantly correlated with intrachromosomal instability." (PMID 31285741, 2019). "The top scoring network in canine mammary tumour was found to have BUB1B as central node in this study." (PMID 30517191, 2018). "BUB1B was also reported to play a role in a series of cancers, such as colon cancer, brain tumor, glioblastoma and breast cancer." (PMID 33665036, 2021).
breast cancer (continued). "BUB1B, which blocks the activation of APCCdc20, is the central component of the mitotic checkpoint for spindle assembly, and it was proved overexpressed in breast cancer and acts as a oncogene." (PMID 33816496, 2021). "Accordingly, many reports have shown that upregulation of BUB1B is related to the recurrence and progression of bladder cancer, gastric cancer, esophageal squamous cell carcinoma, breast cancer, hepatocellular carcinoma and others." (PMID 30778371, 2019). "Interestingly, a majority of Survivin interacting molecules that were found to be significantly regulated by Pirfenidone are also associated with the mitotic spindle (MAD2L1, BUB1, BUB1B, BUB3, CDC20) and were shown to be increased in human breast cancer." (PMID 32039023, 2019). "Furthermore, checkpoint genes, including BUB1B, are expressed at high levels in breast cancer, both at transcriptional (RNA) and translational (protein) levels." (PMID 21785684, 2011). "Five hub genes (TPX2, KIF2C, CDCA8, BUB1B, and CCNA2) associated with the risk of distant metastasis were extracted for further research, which might be used as biomarkers to predict distant metastasis of breast cancer." (PMID 31285741, 2019). "The five potential prognostic biomarkers, i.e., Aurora Kinase A (AURKA), BUB1 Mitotic checkpoint serine/threonine kinase B (BUB1B), Cyclin A2 (CCNA2), Cyclin B2 (CCNB2), and PDZ binding kinase (PBK) were upregulated in breast cancer." (PMID 36980449, 2023). "Elevated expression of the five hub genes AURKA, BUB1B, CCNA2, CCNB2, and PBK are related to poor OS in breast cancer patients." (PMID 36980449, 2023). "AURKA, BUB1B, CCNA2, CCNB2, and PBK, and these hub genes obtained were found to be upregulated (based on log2fold change value) in breast cancer." (PMID 36980449, 2023). "Among these genes are BUB1B and HRAS, which have previously been proven to play important roles in the biological behavior of breast cancer, and the other genes are all genes we fished out." (PMID 36428940, 2022). "One female breast cancer patient tested positive for PGVs in both BRIP1 and NF1, while one patient with splenic cancer harbored PGVs in both SDHB and BUB1B." (PMID 34830767, 2021). "In the current study, we obtained 283 overlapping DEGs and six hub genes (RRM2, CDC20, CCNB2, BUB1B, CDK1, and CCNA2) related to the occurrence and development of breast cancer via comprehensive bioinformatics analysis." (PMID 33083112, 2020). "As a result, there were nearly 2.1% (CDC20, CDK1), 1.2% (RRM2), 0.9% (BUB1B), 0.8% (CCNA2), 0.7% (CCNB2) of breast cancer samples included in cBioPortal had genetic changes." (PMID 33083112, 2020). "Top scoring key networks in benign and malignant mammary tumours were having central nodes of VEGF and BUB1B, respectively." (PMID 30517191, 2018). "Studies have shown that a two-gene ratio (HOXB13:IL17BR) and a five-gene (BUB1B, CENPA, NEK2, RACGAP1, RRM2) molecular grade index (MGI) are predictive of clinical outcomes among early-stage breast cancer patients." (PMID 23497539, 2013). "BUB1B has been studied in multiple tumors, such as colorectal carcinoma, CCA, and breast cancer." (PMID 36979826, 2023). "Nevertheless, whether these drugs could exert therapeutic effects on breast cancer by inhibiting the over-expression of RRM2, CDK1 and CCNA2, or whether CCNB2, BUB1B and CDC20 are promising therapeutic targets still need to be supported by further research." (PMID 33083112, 2020). "BUB1B was expressed higher in invading metastasized breast cancer cells than in those without metastasis." (PMID 29246203, 2017). "In addition, integrating pathway and gene information, we identified five (ID4, ANXA4, CXCL9, MYLK, FBXL7) and six (SQLE, E2F1, PTTG1, TSTA3, BUB1B, MAD2L1) known cancer genes significant for ovarian and breast cancer respectively." (PMID 22759382, 2012).
breast cancer (continued). "Similarly, previous studies had stated that ASPM, CDC20, BUB1B, and CDCA8 expression could be potential poor survival prognostic biomarkers in lung adenocarcinoma, prostate/breast cancer, glioblastoma, respectively." (PMID 36186000, 2022). "Finally, five hub genes (TPX2, KIF2C, CDCA8, BUB1B, and CCNA2) were identified for further research, which might be used as promising biomarkers to evaluate the distant metastasis of breast cancer." (PMID 31285741, 2019).
prostate carcinoma (30 papers, 2016 to 2025). A carcinoma that arises from epithelial cells of the prostate gland. "The advancement and reappearance of carcinoma of the liver, carcinoma of the prostate, pancreatic ductal adenocarcinoma, and multiple additional malignancies have been linked to overexpression of BUB1B." (PMID 39911278, 2025). "High BUB1B expression is associated with poor prognosis and recurrence of multiple types of cancers, including pancreatic, prostate cancer, liver cancers, thyroid carcinoma, and OC." (PMID 41163302, 2025). "In this work, we identified nine carriers of rare germline variants in the BUB1B gene among 462 PrCa patients fulfilling the criteria for hereditary prostate cancer." (PMID 39014450, 2024). "A large number of reports have demonstrated that overexpression of BUB1B was associated with progression and recurrence of bladder cancer, prostate cancer, hepatocellular carcinoma, and some other cancers." (PMID 33431813, 2021). "BUB1B has been demonstrated to enhance tumor proliferation and is associated with worse survival rate in several types of cancer, including prostate cancer, breast, gastric and colorectal." (PMID 31010415, 2019). "However, a large number of reports have demonstrated that overexpression of BUB1B was associated with progression and recurrence of pancreatic ductal adenocarcinoma, prostate cancer, hepatocellular carcinoma, and some other cancers." (PMID 33431813, 2021). "Also, studies have shown that overexpression of BUB1B (budding uninhibited by benzimidazole-related 1) was associated with progression of bladder cancer, hepatocellular carcinoma, and prostate cancer." (PMID 34795689, 2021). "In prostate cancer, BUB1B was found to accelerate cell proliferation by transcriptionally regulating MELK." (PMID 41163302, 2025). "Upregulation of BUB1B also promoted the proliferation of prostate cancer through the regulation of MELK transcription." (PMID 35068350, 2022). "A high expression of BUB1B was also found in prostate cancer, indicating that BUB1B was essential for efficient tumor cell proliferation and correlated with poorer patient outcomes." (PMID 35517426, 2022). "On the other hand, studies have shown that overexpression of BUB1/BUB1B is related to progression and recurrence of various tumors including glioblastoma, pancreatic ductal adenocarcinoma, prostate cancer, gastric adenocarcinoma, and hepatocellular carcinoma." (PMID 33872216, 2021). "Similar findings were reported by two other research groups and showed that BUB1B participates in tumor growth and the progression of prostate cancer and lung adenocarcinoma." (PMID 34253236, 2021). "For example, BUB1B accelerates prostate carcinoma proliferation through transcriptionally modulating MELK." (PMID 34987580, 2021). "BUB1B was identified as an oncogene in prostate cancer through BUB1B‐dependent regulation of MELK transcription." (PMID 32977361, 2020). "High expression of BUB1B can increase proliferation, migration, and invasion of prostate cancer cells." (PMID 31737652, 2019). "The oncogene role of BUB1B has been observed in cancers such as prostate cancer, glioblastoma and gastric cancer." (PMID 31285741, 2019). "BUB1B is upregulated in prostate cancer and CRC tissue and increases cell proliferation." (PMID 39949372, 2025). "CCNE2 and BUB1B promotes the proliferation and migration of prostate cancer cells." (PMID 38778150, 2024). "As observed in our in vitro models, RNA sequencing analysis showed decreased BUB1B expression in the prostate cancer tissue relative to the normal counterpart in both BUB1B carriers, while tumor/normal matched prostate tissues from non-carriers showed an inverse pattern." (PMID 39014450, 2024). "Prior work has documented that BUB1B is a kinase in the mitotic spindle checkpoint and has been implicated to be anomalously expressed in human cancers, such as ductal breast carcinoma, GBM, PDAC, and prostate cancer." (PMID 35068350, 2022).
prostate carcinoma (continued). "BUB1B is also reported to play an oncogenic function in lung adenocarcinoma and prostate cancer." (PMID 36217480, 2022). "A recent study demonstrated that BUB1 mitotic checkpoint serine/threonine kinase B (BUB1B) could promote the proliferation of prostate cancer." (PMID 34298705, 2021). "Overexpression of BUB1B in prostate cancer cells promotes cell proliferation and migration." (PMID 29246203, 2017). "Genes such as BUB1B, ANX1A1, F5, HTR4, and MUC4 can be used as biomarkers to assist in the diagnosis and prognosis of prostate cancer." (PMID 34512870, 2021). "Microarray analysis of prostate (cancer) specimens showed that, similarly to AR expression, UBE2C and BUB1B are significantly upregulated in CRPC tissue compared with benign tissues and androgen-sensitive primary prostate cancer and metastatic tissues." (PMID 30664691, 2019). "Similarly, previous studies have reported abnormally high BUB1B expression in HCC, bladder cancer, prostate cancer, and other cancers." (PMID 41163302, 2025). "Overexpression of BUB1B accelerates the growth of prostatic cancer and predicts a negative prognosis in patients, according to the National Cancer Institute." (PMID 35493295, 2022). "BUB1B accelerates the progression of prostate cancer via the transcriptional modulation of MELK, which can be used as a clinical prognostic factor and drug target for prostate cancer." (PMID 34838000, 2021). "However, the phosphorylated BUB1B, which is tightly regulated through its own activation and subcellular localization, was elevated in the SV40 Tag-derived prostate cancer models." (PMID 30100882, 2018).